SIRT2 (sirtuin 2)
Diseases named in the same sentence as SIRT2 in open-access papers (continued):
Sharing a sentence is not in itself a finding about the gene and the disease.
tumor (continued). "PCAF gene mRNA levels were substantially downregulated in tumor tissue relative to normal cervical epithelial tissue, whereas SIRT2 levels were not significantly different, leading us to hypothesize that SIRT2 may not be a critical regulatory factor in this context." (PMID 38831454, 2024). "However, the role of SIRT2 in tumour angiogenesis has not yet been determined." (PMID 30584257, 2018). "To date, there have been no studies investigating whether SIRT2 is involved in tumour angiogenesis." (PMID 30584257, 2018). "However, it is unclear whether SIRT2 overexpression also increases lifespan in wild-type mice and whether SIRT2-knockout mice that do not develop tumours have a decreased lifespan." (PMID 27875273, 2016). "SIRT2 and SIRT3 have been reported to inhibit tumor progression by de-lactylating non-histone proteins." (PMID 39979245, 2025). "First, they tested the biological role of SIRT2 on CRC cell proliferation, migration and invasion in vitro as well as on tumour growth in a nude mouse model, without examining the effect of SIRT2 in CRC metastasis in vivo." (PMID 32697380, 2020). "In this study, we aimed to examine whether pharmacologic activation of SIRT2 would provide effective prevention and treatment of cisplatin-induced peripheral neuropathy (CIPN) without compromising tumor cell cytotoxic response to cisplatin." (PMID 35875690, 2022).
neurodegenerative disease (53 papers, 2011 to 2025). A disorder of the central nervous system characterized by gradual and progressive loss of neural tissue and neurologic function. "Both nicotinamide analogs attenuated α-synuclein-induced SH-SY5Y viability loss, suggesting that Sirt2 inhibitors with dual binding modes retain translational potential in neurodegenerative diseases." (PMID 38474697, 2024). "Various microRNAs were recently reported to regulate SIRT2 expression via its 3′-untranslated region (UTR), and single nucleotide polymorphisms in the miRNA-binding sites of SIRT2 3′-UTR were identified in patients with neurodegenerative diseases." (PMID 34943825, 2021). "SIRT2 is associated with neurodegenerative diseases, and its inhibition delays the progression of the disease." (PMID 33597872, 2020). "This underscores the value of SIRT2 as a therapeutic target in the most prevalent neurodegenerative diseases that undergo with axonal degeneration associated with redox and energetic dyshomeostasis." (PMID 28984064, 2017). "The small, brain-permeable compound AK7 mediates neuroprotection in neuronal and mouse models of PD and HD, indicating common underlying mechanisms in different neurodegenerative diseases and general benefits of pharmacological SIRT2 inhibition." (PMID 25608039, 2015). "In addition to functioning in tumorigenesis, SIRT2 is also reported to play important roles in neurodegenerative diseases, which are associated with changes in oxidative stress homeostasis." (PMID 38554113, 2024). "Elaborating on the mechanism by which SIRT2 participates in neuroinflammation and neuroimmunology-associated disorders is beneficial to discover novel effective drugs for diseases, varying from vascular disorders to neurodegenerative diseases." (PMID 37215138, 2023). "Increasing evidence has elucidated various pivotal roles that SIRT2 plays in pathological processes, including apoptosis, necroptosis, autophagy, and Inflammatory immune response which were the pathological mechanism underlying cerebral ischemic stroke and neurodegenerative diseases." (PMID 37215138, 2023). "Sirt-1 and Sirt-2 are stress induced proteins that have been implicated in defense mechanisms against agents that may induce oxidative injury, and its induction represents a common feature in a number of neurodegenerative diseases." (PMID 24498895, 2013). "This information is essential to maximize the therapeutic potential of SIRT2 inhibition not only for AD but also for other neurodegenerative diseases." (PMID 37698780, 2023). "This will allow us to evaluate if the pharmacological inhibition of SIRT2 is an effective and safe strategy, and if its usefulness for the treatment of neurodegenerative diseases can be considered." (PMID 37698780, 2023). "Regarding the potential usefulness of SIRT2 inhibitors as pharmacological treatments for neurodegenerative diseases, the implication of HDACs in gene expression and the associated potential for DNA toxicity upon their inhibition present a major concern." (PMID 37698780, 2023). "While the neuroprotection of SIRT1 activation and SIRT2 inhibition have been reported, the common substrates of SIRT1 and SIRT2 and their cooperative effects in neurodegenerative disease have been less established." (PMID 37602729, 2023). "On the one hand, aging induces an increase in SIRT2 levels in the brain, which supports the notion that its pharmacological inhibition is beneficial in different neurodegenerative diseases." (PMID 38132302, 2023). "This will be necessary to validate SIRT2 inhibition as a safe and effective pharmacological strategy for the treatment of AD and other neurodegenerative diseases." (PMID 37698780, 2023). "Consistently, the inhibition of SIRT2 enhances the protective response against such stresses and protects cells, especially neuronal cells, in oxidative stress-related neurodegenerative disease models." (PMID 34943825, 2021).
neurodegenerative disease (continued). "Sirtuin 2 is highly expressed in brain tissue and plays a crucial role in the development of the nervous system and neurodegenerative diseases." (PMID 33014852, 2020). "SIRT1 and SIRT2 can have opposing effects in promoting angiogenesis and in providing neuroprotective effects in neurodegenerative disease models." (PMID 33059738, 2020). "Both SIRT1 activation and SIRT2 inhibition have been identified as good strategies for neurodegenerative diseases." (PMID 29748539, 2018). "A SIRT2 polymorphism has been associated with increased LOAD susceptibility and its level of expression is linked with neurodegenerative disease, likely due to its role in lysosome-mediated authophagic turnover." (PMID 28612290, 2017). "Future work with additional SIRT2 antibodies would be needed to determine the location of SIRT2 along with dual-immunostaining for known neurodegenerative disease biomarkers." (PMID 28634568, 2017). "SIRT2 is an emerging target in neurodegenerative diseases as inhibition of this sirtuin was beneficial." (PMID 28252048, 2017). "Previously published reports on the role of SIRT2 as a modifier of neurodegenerative disease clearly provided a rationale for conducting a phenotypic study in a mouse model of HD." (PMID 22511966, 2012). "Moreover, many papers highlight the importance of SIRT2 in neurodegenerative diseases, inter alia in AD." (PMID 38914873, 2025). "SIRT2 is identified as a potential therapeutic target for neurodegenerative disease." (PMID 39338285, 2024). "And SIRT2 also regulates the immune response in neurodegenerative diseases." (PMID 37215138, 2023). "So far, the results obtained in our study supported the central beneficial effects of SIRT2 inhibition in AD; however, to date, none of the published studies regarding the potential interest of SIRT2 inhibition in neurodegenerative diseases has assessed the peripheral consequences of this treatment." (PMID 37698780, 2023). "SIRT2 plays important role in other neurodegenerative diseases." (PMID 37215138, 2023). "This suggested that SIRT2 can be a potential therapeutic target for neurodegenerative disease." (PMID 37721957, 2023). "The effect of this interaction remains unclear even though SIRT2 also participates in the evolution of neurodegenerative diseases." (PMID 35054829, 2022). "SIRT2 is expressed in almost all brain cells, particularly oligodendrocytes in the central nervous system, and is indirectly involved in cellular processes relevant to the pathophysiology of neurodegenerative diseases." (PMID 36101744, 2022). "There is compelling evidence to support regulation of SIRT1 and SIRT2 that are shuttled between the nucleus and cytoplasm and their inhibition might be beneficial in neurodegenerative diseases, including HD." (PMID 36557263, 2022). "Furthermore, low-molecular compounds, such as Hes1 dimer inhibitors for neural stem cell (NSC) differentiation and histone deacetylase 3 (HDAC3) inhibitors and SIRT2 inhibitors for neurodegenerative diseases, can be used in combination with immunotherapy." (PMID 35214143, 2022). "Such ASO targeting of SIRT2 and microRNAs, which selectively acts on specific types of neurons, could be a desirable strategy for the therapy of neurodegenerative diseases." (PMID 34943825, 2021). "Therefore the role of SIRT2 in neurodegenerative diseases is an intensively studied area of research attracting increasing interest." (PMID 34021216, 2021). "Targeting SIRT2 has been shown to benefit other neurodegenerative diseases." (PMID 34053152, 2021). "Moreover, SIRT2 deletion or pharmacological inhibition has provided beneficial effects in different neurodegenerative diseases." (PMID 33803627, 2021). "In fact, there is not even a consensus whether they are a cause or consequence of age-related neuropathologies, an aspect that is crucial to determine the potential of SIRT2 as a therapeutic target for the treatment of neurodegenerative diseases." (PMID 33803627, 2021).
neurodegenerative disease (continued). "Our study provides another promising strategy to treat the peripheral neuropathy resulting from CMT by inhibiting SIRT2, suggesting that the targeting of SIRT2 might have a general beneficial impact on neurodegenerative diseases." (PMID 34053152, 2021). "This study explores the various modulators that regulate the activity of SIRT1 and SIRT2, which may further assist in the treatment of neurodegenerative disease." (PMID 33597872, 2020). "Histone deacetylase 3 (HDAC3) inhibitors and SIRT2 inhibitors could also be therapeutic agents for neurodegenerative diseases." (PMID 33171799, 2020). "The role of SIRT2 in the pathogenesis of neurodegenerative diseases is controversial." (PMID 31998119, 2019). "Because javamide-II was a stronger inhibitor for Sirt2 than Sirt1, that could be more relevant to neurodegenerative diseases." (PMID 26986569, 2016). "This specificity further strengthens and validates the therapetutic rationale and provides a mechanistic basis for clinical development of brain-penetrant SIRT2 inhibitors as candidate neuroprotectants for PD, HD, and possibly other related neurodegenerative diseases." (PMID 25608039, 2015). "Here, we review the potential roles and effects of SIRT1 and SIRT2 in neurodegenerative diseases." (PMID 23417962, 2013). "The roles of SIRT2 in these neurodegenerative diseases will be discussed in the following sections." (PMID 23417962, 2013). "While it has been suggested that SIRT2 accumulation in the brain with aging could be a compensatory mechanism to combat oxidative stress, other authors have provided evidence on the beneficial effects of SIRT2 inhibition in different age-related neurodegenerative diseases." (PMID 33803627, 2021). "Thus, miRNAs targeting SIRT2 are desirable targets because these are natural endogenous factors; therefore, lipid-based nanoparticle-mediated delivery of miRNAs is a potential delivery mechanism for the treatment of neurodegenerative diseases." (PMID 34943825, 2021). "Our findings therefore, offer SIRT2 as a new tool to segregate GABA from H2O2 production, aiding future research in neurodegenerative diseases." (PMID 39815261, 2025). "Regarding the neuroscience field, where SIRT2 inhibition seems to be an efficient pharmacologic strategy, AK-1, AK-7, and AGK-2 are the most used inhibitors in cellular and in vivo models of neurodegenerative diseases." (PMID 38132302, 2023). "The silent information regulator 2 (SIRT2), a cytoplasmic NAD+-dependent deacetylase, plays important roles in both cerebral ischemic stroke and neurodegenerative diseases." (PMID 37215138, 2023). "To analyze effects of SIRT2, we used AK7, a SIRT2 inhibitor previously reported to exert neuroprotection in some models of neurodegenerative diseases." (PMID 29748539, 2018). "In this context, although numerous studies have proposed the use of SIRT2 inhibitors for different neurodegenerative diseases, to date, none of them has analyzed the potential adverse side effects of this treatment." (PMID 37698780, 2023). "Although inhibition of SIRT2 is thought to have beneficial effects on neurodegenerative diseases such as PD, the deletion of SIRT2 did not appear to effect the disease course of SOD1G93A mice." (PMID 30416425, 2018).
infection (40 papers, 2013 to 2025). The state of being infected such as from the introduction of a foreign agent such as serum, vaccine, antigenic substance or organism. "In infections caused by Mycobacterium tuberculosis and Listeria, SIRT2 activity promotes bacterial survival and infection." (PMID 40317067, 2025). "Pereira J.M., Chevalier C., Chaze T., Gianetto Q., Impens F., MatondoM., Cossart P., Hamon M.A. Infection reveals a modificationof SIRT2 critical for chromatin association." (PMID 38680178, 2024). "Upon infection, Listeria monocytogenes causes SIRT2 accumulation in the nuclear and chromatin spaces." (PMID 37762112, 2023). "Mechanistically, infection causes SIRT2 to interact with the nucleic acid binding protein TDP-43 and localise to genomic R-loops, where H3K18 deacetylation occurs." (PMID 34929015, 2021). "SIRT2 is associated with processes such as carcinogenesis, infection, cell survival, DNA damage, and cell cycle regulation." (PMID 34203972, 2021). "Our previous work identified a novel function of Sirtuin 2 (SIRT2) during infection with the bacterial pathogen Listeria monocytogenes which causes SIRT2-nuclear accumulation." (PMID 34929015, 2021). "SIRT2 activity during infection causes widespread transcriptional reprogramming of the host, resulting in the repression of 272 genes." (PMID 32380645, 2020). "Activation of the c-MET/Phosphoinositide 3-kinase (PI3K)/AKT signaling axis during infection, causes SIRT2, which usually maintains a cytoplasmic localization, to be redistributed to host chromatin where it deacetylates H3K18." (PMID 32380645, 2020). "Altogether, these data support the safety profile of SIRT2 inhibitors under clinical development in terms of susceptibility to infections." (PMID 28894448, 2017). "A similar profile of bacterial burden was observed at day 30 post-infection in the liver (difference of log0.523), although the increased susceptibility of Cre+Sirt2 fl/fl mice was prolonged up to day 60 post-infection (difference of log0.305)." (PMID 26135889, 2015). "It is not yet clear whether this could antagonize the anti-infective activities of SIRT2 modulation, or whether it might prove beneficial and reduce inflammation associated with the response to infection." (PMID 39458938, 2024). "In parallel, SIRT2 levels in the peripheral blood and CNS were associated with markers of neurological damage and brain involution and were more pronounced in individuals who initiated cART later in infection." (PMID 36719240, 2023). "However, following this time bacterial growth in Sirt2-/- plateaus and then decreases after 20 hours of infection which corresponds to the loss of host cells." (PMID 34929015, 2021). "Therefore, although L. monocytogenes infection alone does not significantly impact cell viability, pharmacological inhibition, or loss SIRT2 activity during infection leads to significant cell death and reduced infection." (PMID 34929015, 2021). "Similarly, SIRT2 deficiency also restricts Lm survival during infection in vivo." (PMID 32380645, 2020). "To further confirm the protein expression levels of SIRT2, we used immunofluorescence to detect the expression of SIRT2 in BTCs at 48 h post-infection." (PMID 40317067, 2025). "To investigate the potential role of SIRT2 in BTCs infected with B. abortus A19, we examined the changes in the expression of SIRT2 after 48 h of infection." (PMID 40317067, 2025). "In a follow-up study, the same group discovered that sirtuin 2 (SIRT2), an enzyme with deacetylase activity, regulates the acetylation of cellular proteins including cell cycle proteins during infection and its activation promotes HCMV replication." (PMID 40519923, 2025). "A significant portion of aged SIRT2 KO mice died upon infection with a sublethal dose of SARS-CoV-2." (PMID 40220296, 2025).